LSM12 (LSM12 homolog)
Description:
Nicotinic acid adenine dinucleotide phosphate (NAADP) binding protein. Confers NAADP sensitivity to the two pore channel complex (TPCs) by acting as TPC accessory protein necessary for NAADP-evoked Ca(2+) release.
Synonyms: FLJ30656; PNAS-135
Tractability: PROTAC: ubiquitination databases record sites on it; its protein half-life has been measured.
Gene: Protein-coding gene on chromosome 17 (44,034,328 to 44,067,619, reverse strand). Ensembl gene ENSG00000161654.
Subcellular location: Cytoplasm
Subcellular location (Human Protein Atlas): Cytosol
Gene Ontology:
Molecular function: protein binding; RNA binding
Cellular component: cytoplasm
Genetic constraint (gnomAD): Loss-of-function variants: 0 observed, 20.54 expected, observed/expected ratio (o/e) 0, 90% interval 0 to 0.14. The upper end of that interval is the gene's LOEUF score, 0.14, which puts it in group 1 of 6, group 1 being the genes least tolerant of losing a copy. Missense variants: 97 observed, 197.98 expected, observed/expected ratio (o/e) 0.49, 90% interval 0.41 to 0.58. Synonymous variants: 73 observed, 75.95 expected, observed/expected ratio (o/e) 0.96, 90% interval 0.8 to 1.17.
Homologues: Orthologues: dog LSM12 (100% identical), mouse Lsm12 (100% identical), pig LSM12 (100% identical), rat Lsm12 (100% identical), guinea pig LSM12 (98% identical), chimpanzee LSM12 (87% identical), zebrafish lsm12b (86% identical), tropical clawed frog lsm12 (83% identical), zebrafish lsm12a (77% identical), macaque LSM12 (70% identical), Drosophila melanogaster Lsm12a (32% identical), Drosophila melanogaster Hez (28% identical), and 1 more.
Diseases named in the same sentence as LSM12 in open-access papers:
LSM12 is named in the same sentence as 26 diseases in open-access papers, as found by Europe PMC text mining. Sharing a sentence is not in itself a finding about the gene and the disease. The quoted sentences say what the papers report.
colorectal cancer (6 papers, 2022 to 2025). A primary or metastatic malignant neoplasm that affects the colon or rectum. "A recent investigation revealed that LSM12 exhibits elevated expression levels in colorectal cancer tissues when compared to adjacent normal tissues." (PMID 41171827, 2025). "Recently, LSM12 was found to be overexpressed in colorectal cancer (CRC) and to play an important role in cancer metastasis and progression." (PMID 36371223, 2022). "Consistently, other studies revealed LSM1, LSM2, LSM3, LSM12 as oncogenes which could play a crucial role in growth and progress of breast cancer, basal-like primary tumors, cervical carcinoma or colorectal cancer." (PMID 37007092, 2023). "In colorectal cancer (CRC), LSM12 is highly expressed and participates in the proliferation, invasion, and apoptosis of CRC cells through the WNT/CTNNB1 pathway." (PMID 40425760, 2025).
breast carcinoma (3 papers, 2021 to 2023). "To examine whether Lsm12 is also important for NAADP signaling in other cell lines, we used siRNA to knockdown (KD) Lsm12 expression in SK-BR-3 cells, a breast cancer cell line that was previously shown to be responsive to NAADP7." (PMID 34362892, 2021).
Breast invasive carcinoma (2 papers, 2022 to 2025). "Furthermore, findings from the GEPIA database reveal that LSM12 exhibits significant upregulation in various human malignancies, such as breast invasive carcinoma (BRCA) and colon adenocarcinoma (COAD), indicating its possible role in the pathogenesis of these cancer." (PMID 41171827, 2025).
cervical carcinoma (2 papers, 2023 to 2025). A carcinoma arising from either the exocervical squamous epithelium or the endocervical glandular epithelium. "This study revealed MPP5, SNX7, LSM12, and GALNT3 as genes linked to the prognosis of cervical cancer patients receiving concurrent radiotherapy, through the analysis of the GEO database." (PMID 41171827, 2025). "The prognostic risk model constructed in this study, based on the four genes MPP5, SNX7, LSM12, and GALNT3, demonstrated promising predictive performance for radiotherapy outcomes in cervical cancer patients, particularly in the medium- to long-term follow-up, with an AUC of 0.75 at 3 years." (PMID 41171827, 2025).
amyotrophic lateral sclerosis (1 paper, 2020). Amyotrophic lateral sclerosis (ALS) is a neurodegenerative disease characterized by progressive muscular paralysis reflecting degeneration of motor neurons in the primary motor cortex, corticospinal tracts, brainstem and spinal cord. "A post-transcriptional circuit comprising LSM12 and EPAC1 suppresses neurodegenerative pathologies in C9ORF72-associated amyotrophic lateral sclerosis by establishing the RAN gradient and sustaining nucleocytoplasmic transport." (PMID 33362237, 2020).
cutaneous melanoma (1 paper, 2022). A primary melanoma arising from atypical melanocytes in the skin. "The protein expression of LSM2, LSM4, and LSM12 was upregulated in cutaneous melanoma." (PMID 36371223, 2022).
lung carcinoma (1 paper, 2025). "Lung cancer patients with high LSM12 expression have lower overall survival rates." (PMID 40425760, 2025).
lung squamous cell carcinoma (1 paper, 2025). "Like-Smith protein 12 (LSM12), an RNA-binding protein, is highly expressed in tumor tissues of patients with lung squamous cell carcinoma (LUSC)." (PMID 40425760, 2025). "The molecular characterization of the activity of the RNA-binding protein LSM12 and its interplay with SAMD4A reveals that LSM12 promotes lung squamous cell carcinoma progression by regulating alternative splicing of the ARRB1 gene." (PMID 40425760, 2025).
neuroblastoma (1 paper, 2020). Neuroblastoma (NB) is the most common solid, extracranial childhood tumor. "LSM12 depletion in human neuroblastoma cells aggravated poly(GR)-induced impairment of NCT and nuclear integrity while promoting the nuclear accumulation of poly(GR) granules." (PMID 33362237, 2020).
papilloma (1 paper, 2022). A benign epithelial neoplasm that projects above the surrounding epithelial surface and consists of villous or arborescent outgrowths of fibrovascular stroma. "The results of real time PCR analysis showed that Lsm12 expression was significantly upregulated in OSCC tissues compared with papilloma tissues, which was consistent with the results of microarray data analysis." (PMID 35449073, 2022).
tumor (7 papers, 2021 to 2025). "Cell proliferation, colony formation, Transwell migration and invasion assay and in vivo tumor formation assay were performed to investigate the roles of Lsm12 and two transcript variants of USO1 in OSCC cells." (PMID 35449073, 2022). "These tumor repressive effects of LSM12 knockdown were associated with reducing Ki67 positive proliferating cell population, and increasing apoptotic marker cleaved caspase-3/-9 levels (p < 0.05 or p < 0.01)." (PMID 37303493, 2022). "The present study explored that LSM12 is highly expressed in tumor tissues of LUSC patients and cancer progression by increasing cell proliferation, migration, and invasion, and decreasing the apoptosis of LUSC cells." (PMID 40425760, 2025). "The results showed that SAMD4A acted as a tumor suppressor in LUSC by decreasing the expression of LSM12." (PMID 40425760, 2025). "Overexpression of LSM12 in NCI-H1703 cells promoted the growth of transplanted tumors in nude mice, and knockdown of LSM12 prevented the tumor growth." (PMID 40425760, 2025). "We found that LSM12 is upregulated in the tumor tissues of LUSC in comparison to normal tissues in two datasets." (PMID 40425760, 2025). "Regarding the clinical correlation, high LSM12 expression was significantly associated with the T stage, TNM stage, and Tumor size in LUSC patients." (PMID 40425760, 2025). "In vivo, LSM12 accelerates the tumor growth and metastasis of LUSC cells using male BALB/c nude mice." (PMID 40425760, 2025). "LSM12 depletion in CRC cells decreased the in vivo tumor growth through repression of cancer cell growth and acceleration of cancer cell apoptosis." (PMID 37303493, 2022). "To further investigate the underlying role of LSM12, LSM14A, and LSM14B in tumor cell proliferation and invasion, we transfected SNU-387 cells with si-LSM12, si-LSM14A, and si-LSM14B RNAs." (PMID 35646684, 2022). "Taken together, these findings suggest the critical pro-tumor effects of LSM12, LSM14A, and LSM14B overexpression on HCC tumor cell proliferation and metastasis." (PMID 35646684, 2022). "The CCK-8 assay demonstrated that tumor cell proliferation was notably inhibited in LSM12, LSM14A, and LSM14B depleted SNU-387 cells (P <0.0001)." (PMID 35646684, 2022). "LSM12, LSM14A, and LSM14B overexpression is also associated with higher tumor-related immune checkpoints (e.g., PD-L1, B7-H3, and PVR) expression and increased therapeutic insensitivity to immune checkpoint blockade (ICB)." (PMID 35646684, 2022). "We found that LSM12 was significantly overexpressed in tumor specimens compared with adjacent normal specimens (p < 0.05) in COAD patients and READ patients." (PMID 37303493, 2022). "The H-score showed that LSM12 was upregulated in tumor tissues compared to normal tissues." (PMID 40425760, 2025). "In this study, we found that LSM12 was upregulated in the tumor tissues of patients with LUSC." (PMID 40425760, 2025). "LSM12 knockdown significantly reduced tumor growth and weight (p < 0.05, p < 0.01 or p < 0.001)." (PMID 37303493, 2022). "Moreover, overexpression of LSM12 promoted tumor growth and lung and liver metastasis in vivo." (PMID 40425760, 2025). "In summary, LSM12 was upregulated in LUSC cells and promoted cell proliferation, migration, and invasion of LUSC cells in vitro and enhanced tumor formation and metastasis in vivo." (PMID 40425760, 2025). "The fixed paraffin tumor and normal tissues from the LUSC patients were used to detect the LSM12 expression determined by the immunohistochemical (IHC) assay." (PMID 40425760, 2025). "Immunohistochemistry (IHC) on clinical tumor samples confirmed that the protein expression levels of MPP5, SNX7, LSM12, and GALNT3 were distinctively predictive for CC patients." (PMID 41171827, 2025). "In this study, Tcm infiltration was positively correlated with LSM8 and LSM12 but negatively correlated with LSM2 and LSM4, which was consistent with the effect of genes on tumor prognosis." (PMID 36371223, 2022).
tumor (continued). "Of note, higher expression of tumor-related immune checkpoints (e.g., PD-L1, B7-H3, and PVR) was also observed in tumors with LSM12, LSM14A, and LSM14B overexpression." (PMID 35646684, 2022). "Of note, we identified the potential inhibition effects of LSM12, LSM14A, and LSM14B on tumor immunity, which laid a novel foundation to further explore the role of LSM family members as novel potential therapeutic targets in HCC." (PMID 35646684, 2022). "We also found that tumors with higher expression of LSM12, LSM14A, and LSM14B had higher expression of tumor-related immune checkpoints (e.g., PD-L1, B7-H3, and PVR), which are important for the immunosuppressive phenotype in malignancies." (PMID 35646684, 2022). "Lsm12 overexpression significantly promoted OSCC cell growth, colony formation, migration and invasion abilities, while Lsm12 knockdown showed the opposite trends on these phenotypes and obviously inhibited the tumor formation in vivo." (PMID 35449073, 2022). "Interestingly, LSM12, LSM14A, and LSM14B were observed to play critical roles in the T-cell receptor signaling pathway, suggesting their potential effects on tumor immunity in HCC." (PMID 35646684, 2022). "Additionally, we preliminarily demonstrated knockdown of LSM12, LSM14A, and LSM14B significantly inhibited tumor cell proliferation and invasion." (PMID 35646684, 2022). "In contrast to the important role of WNT signaling in promoting tumor cell migration and invasion in CRC, knockdown of LSM12 not only effectively decreased cell migration (p < 0.001), but also strongly reduced cell invasion in the two CRC cell lines (p < 0.01 or p < 0.001)." (PMID 37303493, 2022). "The results showed that the tumors were formed in all five mice of control group, but no tumor was observed in five mice of Lsm12 knockdown group, which suggested that depletion of Lsm12 could significantly inhibit the tumor formation of OSCC cells in vivo." (PMID 35449073, 2022). "In vivo tumor formation assay showed that no tumor was formed when Lsm12 was knocked down, which might be due to the cell death induced by Lsm12 knockdown." (PMID 35449073, 2022).
cancer (6 papers, 2020 to 2025). A tumor composed of atypical neoplastic, often pleomorphic cells that invade other tissues. "Lsm12 staining spread over the whole cancer tissues while in 91% of normal tissues, Lsm12 staining was negative." (PMID 35449073, 2022). "Studies found that LSM12 plays an important role in many cancers." (PMID 40425760, 2025). "Heretofore, the research on the function of LSM12 in human malignant tumors is still very limited." (PMID 37303493, 2022). "mRNA-seq and RIP-seq analysis demonstrated that LSM12 regulates alternative splicing events and increases exon 13 skipped splicing of ARRB1 and mRNA expression to promoting cancer progression of LUSC." (PMID 40425760, 2025). "Of the eight modeling RBPs, half were upregulated including PABPC1, PRPF6, OAS1, IPO7, and half were downregulated including RBM5, RBM6, LSM12, and FXR7 in cancer cases." (PMID 33584809, 2020). "The function of LSM12 has not been reported in the development of cancer." (PMID 33584809, 2020).
LSM12 also shares sentences with these, for which no sentence is quoted: colon adenocarcinoma (2 papers); adenoid cystic carcinoma (1); cervical squamous cell carcinoma (1); colon cancer (1); endocervical adenocarcinoma (1); esophageal carcinoma (1); glioma (1); lung adenocarcinoma (1); Lynch syndrome (1); oral diseases (1); Oral Squamous Cell Carcinoma (1); respiratory diseases (1); stomach adenocarcinoma (1); uterine corpus endometrial carcinoma (1).